INS (insulin)
Diseases named in the same sentence as INS in open-access papers (continued):
Sharing a sentence is not in itself a finding about the gene and the disease.
Hypoglycemia (continued). "The deficiency of glucagon secretion from islet α-cells makes patients more susceptible to unpredictable episodes of hypoglycemia, even with carefully adjusted insulin doses." (PMID 39744270, 2024). "Congenital hyperinsulinism (CHI) is the leading cause of persistent hypoglycaemia in infants and children, characterised by dysregulated insulin secretion from pancreatic β-cells despite low glucose levels." (PMID 39153498, 2024). "Supplementing insulin with ABA shows promise in reducing the required insulin dose in T1D, thereby lowering the risk of hypoglycemia and enhancing muscle insulin sensitivity and glucose consumption." (PMID 39796447, 2024). "Factors associated with hypoglycemia were older age, comorbidity with heart failure, treatment with dialysis, and receiving a second dose of insulin." (PMID 39274318, 2024). "Hyperinsulinism (HI) due to dysregulation of pancreatic beta-cell insulin secretion is the most common and most severe cause of persistent hypoglycemia in infants and children." (PMID 37454648, 2024). "Unlike other secretagogues, such as sulfonylureas, GLP-1 RA only stimulates insulin secretion in the presence of elevated glucose levels, thereby minimizing the risk of hypoglycemia." (PMID 39720384, 2024). "The major problems relating to insulin therapy are the therapeutic burden for the pregnant woman (discomfort, fear of injections, and cost), the risk of hypoglycemia, and the increased health care resources required for insulin initiation and stabilization." (PMID 39389786, 2024). "Findings remained significant after excluding individuals with baseline use of medications associated with hypoglycemia risk (ie, insulin and sulfonylureas) or with hypoglycemia events." (PMID 39093563, 2024). "Metformin is more cost-effective compared to insulin, has a lower risk of hypoglycemia, and can help to reduce maternal gestational weight gain as well as the occurrence of infants born large for gestational age (LGA)." (PMID 39335553, 2024). "In the last few years, insulin degludec and insulin glargine U300 have shown clear superiority over insulin glargine U100 in terms of risk of hypoglycaemia." (PMID 38679644, 2024). "In cases of high hypoglycaemia risk, de-intensification of sulfonylurea or insulin while intensifying other glucose-lowering medication(s) can thus be necessary and appropriate." (PMID 39407915, 2024). "Conversely, increasing levels of insulin needed to be carefully balanced against the risk of hypoglycemia." (PMID 38570742, 2024). "Congenital hyperinsulinism (CHI) is a rare but severe cause of hypoglycaemia at birth and during infancy, characterised by abnormal insulin secretion." (PMID 38952388, 2024). "Insulin glargine U300 (Gla-300) is one of the long-acting insulin forms that has proven its efficacy in lowering HbA1c levels, providing an effective replacement for basal insulin and protection from the risk of hypoglycemia." (PMID 37581325, 2024). "The results showed sustained HbA1c and TIR reduction, weight loss, lower total daily insulin dose, and less severe hypoglycemia." (PMID 38396657, 2024). "The two antidiabetic drug groups that have been commonly linked with hypoglycaemia in older adults are sulfonylureas and insulin." (PMID 38256662, 2024). "The combination of DAPA + SAXA in insulin-naive patients with poorly controlled T2DM provided similar glycemic control, a lower risk of hypoglycemia, and a meaningful reduction in body weight compared to basal insulin (p<0.0001)." (PMID 39618646, 2024). "Due to their prolonged binding time to the β-cell resulting in prolonged insulin secretion, there is an increased risk of hypoglycemia and weight gain." (PMID 38337487, 2024). "In contrast, clinical trials and real-world studies are indicative of a slightly increased risk of hypoglycemia when GLP-1RAs are combined with insulin or sulfonylureas." (PMID 39568409, 2024).
Hypoglycemia (continued). "First of all, this is associated with the risk of nocturnal hypoglycemia (NH), which is especially high in patients with T1D on basal bolus insulin therapy." (PMID 39518393, 2024). "The product’s monograph warns about the risk of hypoglycemia, especially while changing from other insulin products to Awiqli®." (PMID 39861067, 2024). "All 24 patients exhibited growth hormone deficiency, as evidenced by the insulin-induced hypoglycemia test." (PMID 38828392, 2024). "Due to the risk of hypoglycemia, the initial treatment doses of insulin administered simultaneously with pramlintide must be lowered by 50% or more." (PMID 38338796, 2024). "This real-time feedback can significantly improve the management of insulin levels, reducing the risk of hypoglycemia and other complications." (PMID 39065795, 2024). "Her anxiety symptoms included intense fear of hypoglycemia and insulin, causing her to omit and avoid necessary insulin doses." (PMID 39539363, 2024). "Insulin pump therapy can also reduce the risk of hypoglycaemia and hospitalisation in both younger and older people, as demonstrated by a retrospective study in a Polish population." (PMID 39138689, 2024). "As a result, they cause weight loss and hypoglycemia by increasing insulin sensitivity and decreasing insulin resistance by lowering free fatty acid levels or regulating cellular energy metabolism." (PMID 38727268, 2024). "The weight gain mechanism in insulin-treated T2DM involves factors such as hypoglycemia-associated snacking, inhibited glucose excretion (glycosuria), and decreased metabolic rates." (PMID 39203828, 2024). "Conditions causing non-insulin mediated hypoglycaemia include states of critical illness, cortisol or GH deficiency, drugs, and certain malignant disorders (through production of IGF-I, IGF-II or pro-IGF-II)." (PMID 38451386, 2024). "This suggests that while glibenclamide is effective in stimulating insulin release, it also poses a heightened risk of hypoglycemia, particularly in tight glucose control scenarios." (PMID 38562322, 2024). "Once-weekly basal insulin administration would reduce clinical inertia, increase treatment adherence and improve patients’ quality of life, provided the risk of hypoglycemia remains low." (PMID 38672255, 2024). "Sulfonylurea, administered in a dose of 2/3 of the dose recommended for adults, stimulates the increase of basal and postprandial insulin, with the risk of hypoglycemia." (PMID 39723164, 2024). "Insulin, although the most potent glucose-lowering agent, is associated with higher risks of hypoglycemia and weight gain." (PMID 39723311, 2024). "Patients receiving intensive insulin therapy have a significantly higher risk of developing hypoglycemia than those receiving other types of treatment." (PMID 38872219, 2024). "According to the literature, strong glycaemic control has often been associated with the occurrence of hypoglycaemia, and this behaviour was noted in the generated patients under closed-loop insulin therapy." (PMID 38493243, 2024). "We also found that greater HbA1c TBR was associated with higher risk of ADRD, even after accounting for hypoglycemia events and medication use associated with hypoglycemia (ie, insulin and sulfonylureas)." (PMID 39093563, 2024). "Most of these cases of hypoglycaemia were caused by a reduction in the amount of food ingested, delayed meals after injecting prandial insulin or performing more strenuous physical activities than their usual routine." (PMID 38694587, 2024). "Hirata disease, also known as insulin autoimmune syndrome (IAS), is a rare cause of hypoglycemia, due to the presence of insulin autoantibodies (IAA) in the circulating blood." (PMID 38952701, 2024). "The same study showed that a second dose of insulin is a risk factor for developing hypoglycemia, which we have similarly observed in our study." (PMID 39274318, 2024).
Hypoglycemia (continued). "ACADL deficiency pronounced hypoglycemia, accumulation of lipids, elevated levels of free fatty acids in the bloodstream, and impaired insulin sensitivity in the liver." (PMID 38660376, 2024). "According to the bivariable analysis, receiving insulin or a treatment with a high risk of hypoglycemia were associated with a decreased risk to be overtreated and an increased risk to be undertreated." (PMID 38745127, 2024). "For patients who administer high doses of basal insulin (total daily dose exceeding 80 units; >60% of total daily dose) or are at risk of hypoglycemia, consider reducing the dose of basal insulin by 50–75% to minimize risk of hypoglycemia." (PMID 39458209, 2024). "The ongoing evolution of insulin preparations reflects a shift toward greater convenience, efficacy, and safety, with an emphasis on reducing the risk of hypoglycemia and providing more precise control over blood sugar levels." (PMID 39734941, 2024). "In contrast, AGE supplementation was found to cause significant hypoglycaemia in postprandial blood glucose and insulin levels." (PMID 38778421, 2024). "The serum C-peptide and insulin levels raised the suspicion for pancreatic insulinoma as a cause for recurrent hypoglycemia." (PMID 39434931, 2024). "Patients have also revealed phobia of needles, insulin treatment and risk of experiencing hypoglycemia when taking medications." (PMID 38820419, 2024). "A lower insulin dose at the end of the baseline period was associated with more subsequent hypoglycaemia events in this minimally adjusted analysis." (PMID 38795153, 2024). "In this phase, serum levels of insulin and glucagon and the body’s response to these hormones are unsatisfactory, making hormonal regulation inefficient, which can quickly cause hypoglycemia." (PMID 38756508, 2024). "This has led to the development of insulin analogs with action profiles that enable more flexible treatment regimens and a reduced risk of hypoglycemia." (PMID 39734941, 2024). "This condition confers a considerably increased risk of severe hypoglycaemia, which is the most feared side effect of insulin therapy and a driver of acute morbidity and mortality." (PMID 38427076, 2024). "From antidiabetic therapy, it was found that insulin/SU users were 2.28 times more at risk of hypoglycemia than non-insulin/SU users." (PMID 38243951, 2024). "It is generally known that high and rapid glucose intake can cause rebound hypoglycemia due to the insulin response after administration." (PMID 38914694, 2024). "Conversely, long-acting analogs like insulin glargine and degludec offer a stable, prolonged effect, mimicking basal insulin secretion and reducing the risk of nocturnal hypoglycemia." (PMID 39734941, 2024). "The creation of a desirable therapeutic basal insulin needs to address, at least, 3primary challenges: (a) duration of action, (b) day-to-day and/or within-day SCabsorption variability, and (c) hypoglycemia risk, especially during the overnighthours." (PMID 38224978, 2024). "Small-scale studies in patients on hemodialysis show promising results with decreased risk of hypoglycemia, reduction in insulin dose requirement, and improved glycemic control with use of GLP1-RA15,16." (PMID 39639039, 2024). "In attempts to avoid the morbidity associated with insulin/dextrose-related hypoglycaemia, a range of approaches have been attempted with varying efficacy." (PMID 38871123, 2024). "In the case of HNF1A, the risk of hypoglycemia must be considered, as insulin sensitivity can be normal or increased in individuals with HNF1A‐MODY." (PMID 39511990, 2024). "The driving factor causing hypoglycemia in DNAJC3 deficiency appears to be increased islet insulin secretion, possibly caused by uncontrolled calcium leakage from the ER via the Sec61 complex, rather than insulin leakage from dying beta cells." (PMID 38279270, 2024).
Hypoglycemia (continued). "Traditional antidiabetic medications, such as sulfonylureas and insulin, are associated with increased risks of hypoglycemia and weight gain, which are detrimental to heart failure management." (PMID 39768866, 2024). "Intensive glycaemic control attempts increase the risk of hypoglycemia: patients with T1DM who rely on insulin are at a high risk of experiencing severe hypoglycemia, which is marked by blood glucose levels dipping below 50 mg/dL." (PMID 39539431, 2024). "During PCR, due to a substantial drop in the insulin requirements and a challenge to adjust its dose, the higher risk of mild hypoglycemia is observed." (PMID 39850477, 2024). "The introduction of sensor-augmented pumps with predictive low-glucose suspend and, especially, automated insulin delivery systems is a promising approach to further reduce the risk of hypoglycemia in T1D." (PMID 38611653, 2024). "Incretin-based therapy was also associated with fewer episodes of hypoglycemia and cholelithiasis than insulin therapy." (PMID 39735646, 2024). "The MiniMed670G system is one of the first hybrid closed-loop artificial pancreas that automates the insulin dosage based on real-time glucose levels avoiding human error and reducing risks of hypoglycemia associated with insulin infusion." (PMID 39238969, 2024). "Nonetheless, a child's risk for severe hypoglycaemia was significantly reduced 2.29 times if they were managed with an insulin pump compared to those on multiple daily injections (95% CI, −4.41 to −0.17; p=0.03)." (PMID 40302962, 2024). "Still concerning insulin delivery, such on-demand release mechanisms are crucial in preventing hypoglycemia caused by abrupt or undesired insulin discharge." (PMID 38945949, 2024). "There was little change in satisfaction with Dimension 2, “flexibility of lifestyle after insulin injection”, or Dimension 4, “influence of hypoglycemia caused by insulin on patients”." (PMID 38803476, 2024). "The delayed or prolonged action of conventional insulin increases the risk of hypoglycemia, especially overnight or between meals." (PMID 39734941, 2024). "The utilization of ‘ultrarapid’ insulin has shown promise in reducing the risk of nocturnal hypoglycemia." (PMID 39062173, 2024). "If the individual is not yet on treatment with a GLP-1 RAs, initiating it before prandial insulin should be considered to minimize the risks of hypoglycemia and weight gain associated with intensive insulin therapy." (PMID 38559691, 2024). "SGLT-2 inhibitors are an attractive and favorable option since they demonstrate a potent blood glucose-lowering effect with a low risk of hypoglycemia, owing to their insulin-independent mechanism of action." (PMID 38360626, 2024). "The risk of hypoglycemia (blood sugar </= 70 mg/dL) is theoretically lower than other antidiabetic agents given insulin is released in a glucose-dependent manner." (PMID 38861153, 2024). "The overall beneficial effect on glucose control was also seen when looking at the different types of intervention, and the risk of hypoglycemia was similar between the intermediate-acting insulin and basal-bolus insulin interventions." (PMID 38281042, 2024). "Collectively, these results show that Trpc1/4/5/6–/– mice develop an aggravated insulin-induced hypoglycemia which is associated with reduced plasma adrenaline levels." (PMID 39375537, 2024). "Surprisingly, the combination of metformin with insulin was associated with an increased risk for hypoglycemia in neonates." (PMID 37798604, 2024). "Policies regarding the use of insulin and sulfonylurea can increase the risk of hypoglycemia in type 2 DM patients." (PMID 38243951, 2024). "Congenital hyperinsulinism (HI), due to dysregulated insulin secretion, is the most common cause of persistent hypoglycemia in infants and children." (PMID 39483531, 2024).
Hypoglycemia (continued). "The Control-IQ technology utilized in the t: slim X2 insulin pump accurately forecasts glucose levels with a 30 min lead time and automatically modifies basal rates to mitigate the risk of hyper and hypoglycemia." (PMID 39065641, 2024). "In one of these studies, it was mentioned that the risk of hypoglycemia increased, especially in type 2 DM patients who had comorbidities and were under sulfonylurea, insulin, and hydroxychloroquine treatment." (PMID 39364503, 2024). "For individuals using multiple daily injections (MDI), the basal insulin dose can be reduced by 20–50% before EXE to mitigate hypoglycaemia risk." (PMID 38542818, 2024). "Some antihyperglycemic agents used to treat T2D, such as insulin, sulfonylureas and thiazolidinediones, can lead to weight gain and frequent episodes of hypoglycemia, which are associated with reduced quality of life and increased cardiovascular events." (PMID 38097902, 2024). "Insulin is the most effective therapy for achieving good glycaemic control; however, it is associated with a higher risk of hypoglycaemia, especially with human insulin." (PMID 38694591, 2024). "Once-weekly basal insulin is safe and effective in modestly reducing HbA1c with similar level 2 or 3 hypoglycemic events compared to once-daily insulin, although the risk of level 1 hypoglycemia and weight gain was slightly increased." (PMID 39629047, 2024). "We found that the increases in plasma glucagon levels caused by insulin-mediated hypoglycemia or 2-DG-induced glucopenia were significantly reduced in α-GsKO mice, as compared to control littermates." (PMID 38879678, 2024). "Patients with CKD who also have poorly controlled diabetes, use large doses of insulin or secretagogues, are at risk for hypoglycaemia, or have had a recent episode of diabetic ketoacidosis (DKA) face significant risks if they choose to fast." (PMID 38706994, 2024). "Dulaglutide is a novel long-acting GLP-1 receptor agonist, which has the function of glucose-dependent promotion of insulin secretion, and can reduce the risk of hypoglycemia compared with insulin therapy." (PMID 37255975, 2023). "Hypoglycemia is caused by a mismatch between the BG levels and the circulating insulin concentrations, or by an increased sensitivity to insulin." (PMID 37761419, 2023). "CF patients are usually reluctant to undergo insulin therapy in relation to its route of administration, the risk of hypoglycaemia, and the necessity of monitoring, among other causes which frequently lead to poor treatment compliance." (PMID 37371849, 2023). "Complex insulin regimens have potent blood glucose‐lowering effects, but are associated with hypoglycaemia and weight gain and cause significant treatment burden for the patients." (PMID 36461758, 2023). "Clinically, hypoglycemia caused by an exogenous insulin overdose can be diagnosed via the simultaneous detection of an absolute increase in insulin, a decrease in the C-peptide level, and a decrease in the blood glucose level of <2.8 mmol/L (50 mg/dL)." (PMID 38250973, 2023). "This, in turn, causes neonatal hypoglycaemia at birth due to the loss of glucose from the mother and remaining elevated insulin levels." (PMID 36309618, 2023). "The increasing IAA complexes result in elevated levels of circulating insulin, causing hypoglycemia." (PMID 37519546, 2023). "CGM/FCM, especially in combination with insulin pumps, promises optimal metabolic control through flexible insulin dose adjustment and reduced hypoglycaemia risk." (PMID 38317711, 2023). "Insulin sensitivity is also the highest between 0200 and 0400, causing patients with AI to be at risk of nocturnal hypoglycaemia." (PMID 38053731, 2023). "While intensive insulin therapy has been shown to improve glycaemic management and delay the progression of long-term complications, it also increases the risk of hypoglycaemia." (PMID 37593226, 2023).